APP (amyloid beta precursor protein)
Diseases named in the same sentence as APP in open-access papers (continued):
Sharing a sentence is not in itself a finding about the gene and the disease.
Alzheimer disease (continued). "The Aβ peptides are small amino acidic chains derived from the proteolytic process of the larger amyloid precursor protein (APP), whose aggregation into plaques represents the major hallmark of Alzheimer’s disease along with tau-derived neurofibrillary tangles." (PMID 34199513, 2021). "Using the APP/PS1 mouse model of Alzheimer's disease fed a control (35 mg/kg zinc) or diet deficient in zinc (3 mg/kg zinc), we determined that zinc deficiency accelerated Alzheimer's-like memory deficits without modifying amyloid β plaque burden in the brains of male mice." (PMID 33597269, 2021). "Notably, the aberrant proteolytic processing of amyloid precursor protein (APP) is linked to Alzheimer's disease by producing an excess of the aggregation prone 42-residue form of the amyloid-β peptide." (PMID 34335440, 2021). "APP encodes an amyloid beta precursor protein and is strongly linked to Alzheimer’s disease." (PMID 34685653, 2021). "The amyloid precursor protein (APP) intracellular domain (AICD) is implicated in the pathogenesis of Alzheimer’s disease (AD), but post-translational modification of AICD has rarely been studied and its role in AD is unknown." (PMID 32950104, 2021). "Furthermore, APP mutations are associated with amyloid-β (Aβ) deposition and the pathogenesis of Alzheimer’s disease (AD)." (PMID 34066808, 2021). "Moreover, endocytosis mediated by APPL1/Rab5 constitutes a novel APP-dependent pathogenic pathway in Alzheimer’s disease (AD) and APPL1 has also been found to accumulate as granules around neurons in postmortern human brain of AD." (PMID 33104190, 2021). "Mutations in APP have been found to be a genetic cause of early-onset Alzheimer’s disease (AD)." (PMID 32121263, 2020). "ADAM10 might be best known historically for its role in Notch signaling, and more recently for cleaving the amyloid precursor protein (APP) associated with the pathophysiology of Alzheimer's disease." (PMID 32265938, 2020). "Moreover we report the prevalent role of APP-Aβ degradation genes upon genes involved in APP-Aβ production as well as Mendelian genes causative for Alzheimer’s disease (APP, PSEN1 and PSEN2)." (PMID 32345996, 2020). "Lipid raft aging appears to be exacerbated in Alzheimer’s Disease, which may serve as the underlying contribution to disrupted signal transduction, increased APP processing, and rapid formation of AB aggregates." (PMID 32581851, 2020). "Alzheimer’s disease (AD) mutations in amyloid precursor protein (APP) and presenilins (PSENs) could potentially lead to the production of longer amyloidogenic Aβ peptides." (PMID 32917274, 2020). "For instance, while pathological processing of amyloid precursor protein (APP) to amyloid β in Alzheimer’s disease has been implicated in disrupting autophagy via the BECN1 complex, the normal non-amyloidogenic processing of APP has been associated with neuroprotection in the retina." (PMID 33224023, 2020). "In fact, authors of the amyloid cascade hypothesis recognized that “there may be many causes of Alzheimer’s disease” but postulated “that APP mismetabolism and β-amyloid deposition are the primary events in the disease process”." (PMID 32957083, 2020). "ADAM10 is a member of the ADAM metalloprotease family, which is a key proteinase responsible for the processing of amyloid precursor protein (APP) to prevent the excessive production of the pathogenic amyloid β (Aβ) peptide, a hallmark of Alzheimer’s disease (AD)." (PMID 31114485, 2019). "Alternative splicing of Amyloid precursor-like protein 2 (Aplp2) is known to regulate inclusion of a bovine pancreatic trypsin inhibitor (BPTI) Kunitz domain and this domain is known to regulate proteolysis of the related protein APP, the amyloid precursor protein implicated in Alzheimer’s disease." (PMID 30977723, 2019). "Notably, APP has been implicated in a number of neural disorders, including Alzheimer disease and intellectual disability." (PMID 31174177, 2019).
Alzheimer disease (continued). "Similarly to prion diseases, a minority of Alzheimer’s disease cases is due to dominantly inherited mutations affecting mainly the APP gene." (PMID 31547531, 2019). "Additionally, adults with DS are at an ultra-high risk of Alzheimer’s disease (AD) (lifetime prevalence 90%) attributed to triplication of the APP gene which is located on chromosome 21." (PMID 30877793, 2019). "Alzheimer disease is linked to variants in amyloid-β-protein precursor (APP), presenilin-1, and presenilin-2 (PS1 and PS2) genes, which lead to neuropathological characteristics of advanced accumulation of β-amyloid in the brain and the dyruption of synaptic LTP transmissions." (PMID 31133796, 2019). "Some of these are rare and ancestry specific, for example, a LoF allele within the amyloid-β precursor protein (APP)-coding region in Icelanders reduces amyloid-β aggregation and may offer protection against Alzheimer’s disease." (PMID 31002796, 2019). "Interestingly, calsyntenin-1 levels are reduced in Alzheimer’s disease brains and this suggests that calsyntenin-1 loss contributes to damaged APP transport in Alzheimer’s disease." (PMID 31806024, 2019). "Transgenic mice with a mutated human APP gene that were designed to promote Aβ accumulation and deposition formed neuronal plaques; however, neuronal loss did not occur in the hippocampus or association cortex, which is characteristic of Alzheimer’s disease." (PMID 29879811, 2019). "Hence inheritance of one copy of this gene results in 100% penetrant Alzheimer’s disease–the mutation poisons endogenous APP." (PMID 31849608, 2019). "Although mutations in amyloid precursor protein (APP) and its proteases presenilin-1 and 2 have a causative relationship with the onset of familiar form of Alzheimer’s disease (FAD), overt manifestation of clinical AD is often preceded by a prolonged incubation period." (PMID 31453805, 2019). "In 660 Alzheimer’s disease cases with earlier onset ages of ≤65, 4 out of 13 (31%) previously-published rare pathogenic and protective mutations in APP, PSEN1, and PSEN2 genes were undetected by the default one-pipeline approach but recovered by the multi-pipeline approach." (PMID 29661148, 2018). "Another noteworthy DMR was associated with APP-cleaving enzyme 2 coding gene (BACE2) encoded protein that cleaves amyloid precursor protein into amyloid beta peptide, and is implicated in the pathogenesis of neurodegenerative diseases including Alzheimer’s disease." (PMID 30545422, 2018). "Because yata mutation results in reduced synaptic transport of the Drosophila APP orthologue, we investigated whether a yata mutation would affect the phenotypes of the Drosophila model of Alzheimer’s disease." (PMID 30226901, 2018). "And how should we interpret the “Alzheimer’s disease-protective” mutation of APP, A673T?" (PMID 30150923, 2018). "Genetic mutation or gene duplication of APP causes Alzheimer's disease." (PMID 30226901, 2018). "Amyloid beta precursor protein (APP), while frequently implicated in Alzheimer's disease (AD) and relating to the formation of amyloid plaques, may also interact with reelin and modulate synaptic plasticity." (PMID 30498460, 2018). "Thus, the question arises of what causes the abnormal processing of endothelial APP in Alzheimer’s disease." (PMID 28617802, 2017). "Notably, the core genes were connected to APP (encoding amyloid beta precursor protein), a major player in Alzheimer’s disease that is known to have immune and inflammatory components." (PMID 28428554, 2017). "Alzheimer’s disease (AD) is ultimately linked to the amyloid precursor protein (APP)." (PMID 28197076, 2017). "Investigating an Alzheimer's disease (AD) mouse model [transgenic for five familial AD (5XFAD) mutations associated with the Amyloid precursor protein (APP) and Presenilin 1], as well as brain samples from AD patients, Jung and colleagues reported a reduction in SIRT6 protein in these models." (PMID 28642687, 2017).
Alzheimer disease (continued). "HN was the first MDP discovered in 2001 by cloning a cDNA library to the 16S rRNA region to screen for molecules conferring neural apoptotic resistance against a mutated amyloid precursor protein (APP) from the unaffected portion of brain tissue of an Alzheimer disease (AD) patient." (PMID 28814984, 2017). "Alzheimer disease (AD) is a complex and common progressive neurodegenerative disease that reflects multifactorial gene mutation (i.e., APP, Presenilin (PSEN) 1 and PSEN 2, ApoE4) as a hallmark of the etiology of familial AD (FAD) and Sporadic AD (SAD) in the elderly population." (PMID 28072821, 2017). "The connection of these genes with APP in the core subnetwork is of great interest and is supported by a number of studies indicating that asthma and Alzheimer’s disease (AD) may share common underlying mechanisms." (PMID 28428554, 2017). "N-terminal truncated Aβ peptides are almost exclusively generated by meprin β from the complete APP wildtype sequences or from APP carrying familiar Alzheimer disease mutations at the γ–secretase cleavage site but bearing the wildtype sequence around the β-cleavage site." (PMID 28105004, 2016). "Interestingly, PSEN1 and APP, genes whose mutation are known to be linked to early onset Alzheimer’s disease, are closely linked to this pathway." (PMID 27585646, 2016). "Mutations in APP have been implicated in Alzheimer’s disease and cerebroarterial amyloidosis." (PMID 26833210, 2016). "BACE2, also called Asp1 (aspartyl protease 1) or memapsin 1 (membrane-anchored aspartic protease of the pepsin family), is a transmembrane aspartic protease and the homolog BACE1, the well-known enzyme implicated in Alzheimer’s disease that cleaves the Amyloid β Precursor Protein (APP)." (PMID 27589732, 2016). "APP is a single transmembrane protein that has been linked to Alzheimer disease." (PMID 26673618, 2016). "The APP gene lies on Hsa21 and encodes the amyloid precursor protein that is at the heart of the amyloid cascade hypothesis of Alzheimer disease." (PMID 26528151, 2015). "Furthermore, 20 μM DHEC caused the accumulation of APP-CTFs and led to ~35% reduction in total Aβ in fibroblast cells from an Alzheimer’s disease patient carrying a missense mutation (A246E) in the presenilin 1 (PS1) gene." (PMID 26567970, 2015). "APP was selected for validation due its repeated association with various human neurodegenerative conditions, including but not limited to Alzheimer's disease, prion diseases, tauopathies, murine neurodegenerative disease models, and as part of an acute phase response to neuronal injury." (PMID 26364976, 2015). "Amyloid precursor protein (APP) is known as a pathological hallmark of Alzheimer's disease (AD)." (PMID 25591988, 2015). "Indeed, many mouse models of Alzheimer's disease (AD), such as Presenilin-1 with both M146V and ΔExon9 mutations in knock-in mice and transgenic mice with the Swedish APP mutation, showed decreased adult neurogenesis." (PMID 25941474, 2015). "Up-regulation of GSK-3 activity leads to phosphorylation of the amyloid precursor protein (APP) and the protein tau, both of which are associated with the pathological processes that lead to the hallmarks of Alzheimer's disease (AD), amyloid-β plaques and neurofibrillary tangles." (PMID 26578864, 2015). "For instance, let-7d, miR-191 and miR-301a make part of a unique circulating 7-miRNA signature that can distinguish patients with Alzheimer’s disease from normal controls, and miR-20a and miR-106b are both implicated in transcriptional inhibition of Alzheimer’s amyloid precursor protein (APP)." (PMID 25333486, 2014). "SORCS1 has been previously implicated in neurodegeneration by genetic association with Alzheimer's disease as well as with APP processing whereby reduced expression of SORCS1 is associated with increased γ-secretase processing and Aβ levels possibly as a result of altered trafficking." (PMID 24833721, 2014).
Alzheimer disease (continued). "The analysis of the Mendelian families with Alzheimer’s disease led to the identification of APP and Presenilin mutations and the formulation of the amyloid cascade hypothesis." (PMID 25113539, 2014). "Dysfunctions in the metabolic processes of amyloid precursor protein (APP) are widely hypothesized to underlie Alzheimer’s disease (AD)." (PMID 25213836, 2014). "The β-site APP cleaving enzyme 1 (BACE1) is an important target for causing Alzheimer's disease (AD), due to the brain deposition peptide amyloid beta (Aβ) require cleavages of amyloid precursor protein (APP) by BACE1 and γ-secretase, but treatments of AD still have side effect in recent therapy." (PMID 24900984, 2014). "Also the relative contribution of PSEN1, PSEN2, and APP mutations to early onset Alzheimer's Disease (EOAD) is the subject of considerable controversy, and mutation frequency is highly dependent upon the studied population." (PMID 24377094, 2013). "Alzheimer’s disease-causing mutations in APP result in an overall increase of the production of Aβ." (PMID 23801962, 2013). "We applied the AFT-BiFC system to show that the Swedish APP familial Alzheimer’s disease mutation increases AFT complex formation, consistent with the notion that AICD mediated nuclear signaling mainly occurs following APP processing through the amyloidogenic β-secretase pathway." (PMID 24086696, 2013). "Less than 1% of Alzheimer's disease cases are familial, with autosomal dominant mutations described in only three genes that lead to early onset disease; APP, presenilin 1 (PSEN1) and presenilin 2 (PSEN2), both of the latter encoding components of the γ-secretase pathway." (PMID 24133413, 2013). "Interestingly, best known for their association with Alzheimer’s disease, amyloid precursor protein (APP) and the microtubule-associated protein tau (MAPT) were elevated in maters." (PMID 23874981, 2013). "Moreover, PCSK9 has been shown to regulate levels of BACE1, one of the enzymes that cleaves APP to form the Aβ peptide associated with Alzheimer disease." (PMID 23430252, 2013). "APP/PS1 double-transgenic mouse models of Alzheimer’s disease (AD), which overexpress mutated forms of the gene for the human amyloid precursor protein (APP) and presenilin 1 (PS1), have provided robust neuropathological hallmarks of an AD-like pattern at early ages." (PMID 29805876, 2013). "Abnormal deposition of neuriticplaques is the uniqueneuropathological hallmark of Alzheimer’s disease (AD).Amyloid β protein (Aβ), the major component of plaques, is generated from sequential cleavage of amyloidβ precursor protein (APP) by β-secretase and γ-secretase complex." (PMID 23894546, 2013). "Interestingly, in a mouse model of Alzheimer's disease, MyD88 deficient and APP over-expressing mice had an accelerated disease process pointing to a role for MyD88 in clearance of amyloid." (PMID 22363497, 2012). "APP was initially implicated in the etiology of Alzheimer's disease by a number of facts." (PMID 24278680, 2012). "Activation of the α-secretase processing pathway of amyloid precursor protein (APP) is recognized as an important mechanism which diverts APP processing from production of beta-amyloid (Aβ) to non toxic sAPPα, decreasing Alzheimer’s disease (AD) plaque formation and AD-associated cognitive deficits." (PMID 22700373, 2012). "It is also unclear as to whether NADPH oxidase may play a role in the induction of Alzheimer's disease (AD)-related proteins such as amyloid processing protein (APP) and β-amyloid, which have been implicated in the pathology of TBI." (PMID 22485176, 2012). "The Etiology of Alzheimer’s Disease are related to some major risk factors including Apolipoprotein E4, A2 Macroglobolin, Persenilin 1,2.Amyloid Precursor Protein (APP) and many neurotoxins that accelerate Beta-Amyloid deposits in the brain and impaired memory process." (PMID 24551770, 2012).
Alzheimer disease (continued). "In other pathways, caspase-6 is also known to cleave cytoskeletal and structural proteins, such as the microtubule-associated protein tau and amyloid precursor protein (APP), and caspase-6 is detected in neurodegenerative diseases, such as Alzheimer's disease and Huntington's disease." (PMID 22363841, 2012). "Human Alzheimer precursor protein (APP) gene was brought to the forefront of scientific interest in the late 80's when protein sequencing of the major component of the amyloid plaques, the amyloid β peptide (Aβ) implicated APP in the development of Alzheimer's disease (AD)." (PMID 22319430, 2012). "The major Alzheimer's disease genes implicated by the recent GWAS data, as well as APP and gamma secretase, and previous GWAS results are majoritarily involved in pathogen entry and defence, particularly in relation to herpes simplex, but also to other relevant pathogens, and in the immune network." (PMID 22254144, 2011). "Our studies also suggest the possibility that there may exist in the human population alleles of APP that encode substitutions in the glycine zipper regions that protect against Alzheimer's disease." (PMID 21861874, 2011). "Primary neurons from GD3S−/− mice are resistant to neurotoxicity induced by amyloid-β or hyperhomocysteinemia, and when GD3S is eliminated in the APP/PSEN1 double-transgenic model of Alzheimer's disease the plaque-associated oxidative stress and inflammatory response are absent." (PMID 22195039, 2011). "Abnormal accumulation of APP protein has long been associated with Alzheimer's disease." (PMID 22373040, 2011). "In addition to nucleotide variations, an increased dosage of the APP gene is also known to cause Alzheimer disease (AD)." (PMID 22044463, 2011). "APP expression misregulation can cause genetic Alzheimer's disease (AD)." (PMID 21982160, 2011). "Tip60 HAT activity has been implicated in the age-related neurodegenerative disorder Alzheimer's disease (AD) via its HAT dependent complex formation with the C-terminal fragment of the amyloid precursor protein (APP) known as the APP intracellular domain (AICD) and linker protein Fe65." (PMID 22046262, 2011). "The rationale for pursuing APP proteolytic stimulation via α/γ-cleavage is consistent with the growing body of evidence pointing to a loss of function associated with the genetically heritable Familial Alzheimer's disease (FAD) mutations." (PMID 20161760, 2010). "The amyloid precursor protein (APP) is genetically associated with Alzheimer's disease (AD)." (PMID 18070361, 2007). "The APP gene consists of 17 exons in total and encodes several isoforms produced through the alternative splicing of exons 7 and 8, three of which are relevant to Alzheimer’s disease as a neurodegenerative condition (isoforms 695, 751, and 770) and are expressed solely in the central nervous system." (PMID 40869138, 2025). "Alzheimer disease (AD) is a neurodegenerative disease associated with the improper cleavage of APP by γ-secretase, leading to increased production of the amyloidogenic Aβ-42 peptide." (PMID 39865938, 2025). "Less than 1% of all AD cases (10% of EOAD) have early onset autosomal dominant Alzheimer disease (ADAD) with a disease-causing variant in amyloid-β precursor protein gene (APP), presenilin 1 (PSEN1) or presenilin 2 (PSEN2)." (PMID 39849058, 2025). "In addition, while our study demonstrates that DSS and its disassembled prescriptions ameliorate Alzheimer’s disease-associated cognitive deficits and gut dysbiosis in APP/PS1 mice, we acknowledge a critical limitation highlighted by recent metaproteomic evidence." (PMID 40822397, 2025). "Alzheimer’s disease (AD) is a neurodegenerative disease initially defined by a proteinopathy associated with the accumulation of amyloid beta (Aβ) peptides that are produced through the sequential cleavage of the amyloid precursor protein (APP) by the β- and the γ-secretases." (PMID 38806484, 2024).